SMAD2 (SMAD family member 2)
Diseases named in the same sentence as SMAD2 in open-access papers (continued):
Sharing a sentence is not in itself a finding about the gene and the disease.
oral cancer (7 papers, 2020 to 2024). "TGF-β, SMAD2, TNFα, and NFκB downregulation was associated with a decrease in oral cancer cell movement." (PMID 39156270, 2024). "The progression of oral cancer cells is also associated with SMAD2 signaling." (PMID 39156270, 2024). "We then examined the mRNA expression of transforming growth factor-beta (TGF-β), suppressor of mothers against decapentaplegic 2 (SMAD2), tumor necrosis factor alpha (TNFα), and nuclear factor kappa B (NFκB) signaling molecules in oral cancer cell lines." (PMID 39156270, 2024). "We discovered that naringin treatment dramatically reduced TGF-β, SMAD2, TNFα, and NFκB gene expression in oral cancer cells." (PMID 39156270, 2024). "The anomalous activation of TGF-β, SMAD2, TNFα, and NFκB signaling in oral cancer cells can encourage the growth and spread of tumors." (PMID 39156270, 2024). "While our work does not delve into the specific mechanisms responsible for this anti-cancer impact, it does indicate that the extract's ability to regulate TGF-β/Smad2 signalling may have wider ramifications for the advancement of oral cancer." (PMID 38034260, 2023). "Therefore, we report that OLA1 can inhibit the EMT process induced by TGFβ/SMAD2, thereby increasing the drug sensitivity of oral cancer cells to PTX." (PMID 32928102, 2020). "Oral cancer cell development and metastasis are strongly impacted by the TGF-β, SMAD2, TNFα, and NFκB signaling pathways." (PMID 39156270, 2024). "This study investigated the impact of naringin on oral cancer cell line mediated by the TGF-β, SMAD2, TNFα, and NFκB signaling pathways." (PMID 39156270, 2024). "Overall, this study highlights the promising role of naringin as a pro-apoptotic and cytotoxic phytochemical regulating the gene expression of Bcl-2, TGF-β, SMAD2, TNFα, NFκB, BAD, BAX, and caspase-3, thereby treating oral cancer." (PMID 39156270, 2024). "In summary, this research emphasizes the potential of naringin as a cytotoxic and pro-apoptotic phytochemical that modulates the expression of Bcl-2, TGF-β, SMAD2, TNFα, NFκB, BAD, BAX, and caspase-3 genes, ultimately aiding the treatment of oral cancer." (PMID 39156270, 2024). "We report the molecular docking analysis for oral cancer drug, Imiquimod with TGF-β signaling pathway targets such as Smad2, GATA2, and MAFG which are mainly plays a crucial role in regulation of Epithelial Mesenchymal Transition(EMT) in cancer cells." (PMID 37822834, 2023). "To elucidate the role of TGFBR3 in TGF-β signaling in oral cancer cells, we determined the effect of TGFBR3 expression on phosphorylation of SMAD2/3, an activation mark of the canonical TGF- β pathway, with or without SB431542, an inhibitor of TGFBR1." (PMID 32471132, 2020).
preeclampsia (7 papers, 2017 to 2023). Preeclampsia is a hypertensive disorder of pregnancy that is characterized by new-onset hypertension with proteinuria presenting after 20 weeks of gestation, and depending on mild or severe forms may initially present with severe headache, visual disturbances, and hyperreflexia. "TGF-βs—through activation of downstream signaling mediators—and SMAD2/3 are triggering factors for preeclampsia, resulting in abnormal placental development." (PMID 35207707, 2022). "We also found that the expression of AAT, Id4 and Smad2 was significantly decreased in preeclampsia tissues compared with normal control, confirming our results in vitro and animal model." (PMID 29348884, 2017). "In present study, we demonstrated that AAT prevented progression of preeclampsia by enhancing Smad2 phosphorylation and Id4 gene expression." (PMID 29348884, 2017). "AAT protected the cells from hypoxia/reoxygenation injury and prevented preeclampsia progress through Id4 that activated by Smad2." (PMID 29348884, 2017). "Reduced Id4 expression and Smad2 phosphorylation were observed in preeclampsia animal model, which was also confirmed in human placenta tissues." (PMID 29348884, 2017). "In addition, AAT protected HUVEC cells from hypoxia/reoxygenation injury and relieved preeclampsia symptoms through Smad2/Id4 axis." (PMID 29348884, 2017). "These phenomena were also confirmed in protein levels evaluated by western blot, suggesting that AAT may through regulating Id4 and Smad2 to contribute to preeclampsia." (PMID 29348884, 2017). "Preeclampsia resulted in inactivation of Id4 and Smad2, which was re-activated by AAT." (PMID 29348884, 2017). "Phosphorylated SMAD2 and SMAD7 expression are also increased in early onset preeclampsia as compared with an age matching control." (PMID 33673360, 2021). "In addition, we collected six normal placenta and preeclampsia placenta tissues from human to examine the expression of AAT, Id4 and Smad2." (PMID 29348884, 2017). "In addition, ALK5 expression and SMAD2 activation has been shown to be increased in early onset preeclampsia, but not in late onset preeclampsia." (PMID 33673360, 2021). "In preeclampsia, which is a non-PAS-like disorder but a typical abnormal placental disorder, the abnormal expression of Smad2 affects extrachorionic villus differentiation, which in turn affects soluble Flt-1 activity." (PMID 37762005, 2023).
scleroderma (7 papers, 2009 to 2025). Scleroderma is a rare autoimmune connective tissue disorder characterized by abnormal hardening of the skin and, sometimes, other organs. "WGCNA analysis identified Smad2 as a hub gene in the treatment of scleroderma fibroblasts by ADSC supernatant, suggesting that the paracrine factors of ADSCs exerted antifibrotic effects by inhibiting the TGF-β1/Smad2 pathway." (PMID 40386129, 2025). "We observed critical changes in the scleroderma epidermis; showing significantly increased nuclear translocation of phosphorylated Smad2/3, consistent with active TGFβ signaling in SSc keratinocytes." (PMID 26217927, 2015). "Nimbolide attenuated the progression of scleroderma by controlling inflammatory factors such as TNF-α, IL-1β, and p-NF-κB and by downregulating the TGF-β/Smad signaling axis (inhibition of TGF-β expression and Smad2/3 protein phosphorylation)." (PMID 34258301, 2021). "Moreover, increased Smad2 and Smad3 phosphorylation by TGF-β was observed in scleroderma fibroblasts." (PMID 31937306, 2020). "While Nab2 expression was dramatically up-regulated in epithelial cells in scleroderma skin biopsies, consistent with activated TGF-β signaling in the fibrotic milieu, dermal fibroblasts from biopsies that were strongly immunopositive for Egr-1 and phospho-Smad2 showed a paucity of Nab2 expression." (PMID 19888474, 2009).
squamous cell carcinoma (7 papers, 2009 to 2023). A carcinoma arising from squamous epithelial cells. "Furthermore, a survival plot showed that the high expression of some hub genes (FOXO3, CCR5, PECAM1, ESR1, and SMAD2) was associated with high risk of death in patients with esophageal carcinoma and other squamous cell carcinomas." (PMID 33747034, 2021). "It has been shown that Cdk2ap1 is activated by TGF-β-Smad2 and mediates TGF-β induced growth arrest in normal diploid cells and the loss of Cdk2ap1 expression in squamous cell carcinoma is correlated with disrupted TGF-β-Smad signaling pathway." (PMID 19229340, 2009). "Likewise, the expression of ΔNp63 has been shown to be induced by TGF-β via Smad2 and IKKα in the A431 epidermoid carcinoma cell line." (PMID 37638000, 2023). "Knocking down of kindlin-2 attenuated the TGF-β-stimulated Smad2/3 phosphorylation while the higher expression of kindlin-2 promoted TGF-β mediated cell signaling in fibroblasts and squamous cell carcinomas." (PMID 34638957, 2021). "Activated H-Ras over-expression in squamous carcinoma cells demonstrated that oncogenic Ras stimulated TGF-β-induced transcription and enhanced TGF-β-induced phosphorylated Smad2 levels." (PMID 29534718, 2018). "During tumour progression from keratinocyte towards squamous carcinoma then to invasive spindle cell carcinoma, TGF-β signaling activity was dramatically increased and the constitutively activated Smad2 was observed in invasive spindle tumour cells only." (PMID 29534718, 2018). "TGF-β may also maintain the quiescent state of CSCs by phosphorylating SMAD2 and SMAD3 in squamous cell carcinoma." (PMID 35413945, 2022). "Furthermore, in a series of well-characterized tumour cell line derived from sequential stages of mouse skin carcinogensis, activated H-Ras over-expression in squamous carcinoma cells demonstrate that Ras stimulates TGF-β-induced transcription and enhances TGF-β-induced phosphorylated Smad2 levels." (PMID 29534718, 2018).
Stroke (7 papers, 2010 to 2026). Sudden impairment of blood flow to a part of the brain due to occlusion or rupture of an artery to the brain. "Interestingly, after stroke, Smad2 and Smad3 are involved in reactive astrogliosis and glial scar formation." (PMID 40362186, 2025). "In this study, we show the effect of 1,25-D3 act on TGF-β/Smad2/3 in stroke." (PMID 35369317, 2022). "Hence, the present findings suggest a new way of action of EVs derived from OGD-preconditioned microglia by regulating the TGF-β/Smad2/3 pathway in order to promote tissue regeneration and neurological recovery in stroke mice." (PMID 34753919, 2021). "To confirm the increase in TGFβ signaling we detected by luciferase activity, we performed a western blot on brain extracts from the ipsilateral hemisphere of mice sacrificed before, and 7 days after stroke, for phosphorylated Smad2 (pSmad2), a downstream mediator of TGFβ signaling." (PMID 20937129, 2010). "Bioinformatics studies revealed that Smad2, a mediator of TGF-β signaling involved in stroke recovery, is a target for miR-155." (PMID 40362186, 2025). "Results showed that the expression of VDR, TGF-β, p-Smad2/Smad2, p-Smad3/Smad3, and VEGF in the periinfarcted cortex was significantly higher than DMSO group 3 days after stroke." (PMID 35369317, 2022). "1,25-D3 activated VDR then up-regulated TGF-β/Smad2/3 signaling pathway and enhanced VEGF production, which contribute to promoting angiogenesis and improving stroke outcomes in rats after stroke." (PMID 35369317, 2022). "Our results suggest that 1,25-D3 promotes angiogenesis by up-regulating TGF-β/Smad2/3 signaling pathway via VDR activation, thereby alleviating ischemia/reperfusion injury and improving stroke outcomes in rats." (PMID 35369317, 2022). "We found that delayed treatment with recombinant GDF11 (rGDF11) at 7 days after stroke promoted neurogenesis and angiogenesis and improved behavioral outcome by regulating the TGF-β/Smad2/3 signaling pathway." (PMID 30061815, 2018). "We also demonstrated that treatment with rGDF11 from 7 days after stroke significantly enhanced neurogenesis and angiogenesis and improved functional outcome through regulating the TGF-β/Smad2/3 signaling pathway." (PMID 30061815, 2018).
thoracic aortic aneurysm (7 papers, 2014 to 2024). An aneurysm formed in the wall of the proximal portion of the descending aorta proceeding from the arch of the aorta. "Modification of the histone H3 marker near the promoter of the SMAD2 gene has been observed in patients with BAV-associated thoracic aortic aneurysm as an epigenetic mechanism behind SMAD2 overexpression." (PMID 34071740, 2021). "Modification of the histone H3 marker near the promoter of the SMAD2 gene may be observed in patients with thoracic aortic aneurysm; this is considered to be an epigenetic mechanism linked to SMAD2 overexpression." (PMID 36673063, 2023). "In addition, in human thoracic aortic aneurysms (TAAs), SMAD2 was upregulated, compared the level in normal aortas, and H3K9/14 acetylation and H3K4 methylation were involved in SMAD2 overexpression in TAAs." (PMID 32070413, 2020). "This study highlights the important role of Smad2 and TGF-β in thoracic aortic aneurysms." (PMID 25238161, 2014).
viral infections (7 papers, 2015 to 2023). "This included genes of IRF3-mediated induction of type I IFN and SMAD2/3 signaling, which are essential pathways in regulating type 1 interferons during bacterial and viral infections." (PMID 37664632, 2023). "Together, these data confirm that both KSHV vFLIP and vCyc regulate SMAD2 in the context of viral infection in cells of epithelial and endothelial origin, albeit at different efficiencies." (PMID 26545119, 2015). "The TGFβ signaling module consists, besides the TGFβ–pathway, of related pathways regulating SMAD2/3 signaling, HIF-1 alpha transcription, coregulation of androgen receptor activity, FOXA1 transcription and some pathways related to viral infections." (PMID 26701206, 2016). "It is unknown whether—(a) respiratory viruses like RSV activates SMAD-2/3 pathway; and (b) SMAD-2/3 pathway play any role in regulating virus infection and innate immune response." (PMID 28018859, 2016). "The signal transducer SMAD2 is activated by TGFβ and this signaling pathway is suggested to play an important role in apoptosis as well as in virus specific CD8+ T cell responses during chronic viral infections, such as LCMV infection in mice and HIV/SIV infection in humans and NHP, respectively." (PMID 26986062, 2016).
adenoma (6 papers, 2016 to 2025). A neoplasm arising from the epithelium. "TGF-β1 addition (390 pM) resulted in the detection of phosphorylated p-Smad2 and p-Smad3 in both the Smad4+/+ and Smad4Δ/Δ adenomas as expected." (PMID 40348815, 2025). "(F) Western blotting for p-Smad2/3, p21, Axin1, β-Catenin, Cyclin D1 in adenomas of WT and miR-31−/− mice resulting from AOM-DSS treatment." (PMID 28870287, 2017). "In the benign adenoma stage, the essentiality of four control nodes, beta-arrestin, P115RhoGEF, Smad2/4, and ERK were observed as 0.039, 0.085, 0.017, and 0.239, respectively." (PMID 27765040, 2016). "Both p-Smad2 and p-Smad 1/5/8 labelling were detected in adenoma at higher levels from ApcΔ/ΔSmad4Δ/Δ compared to normal tissue and littermate control adenoma, consistent with either TGF-β alone or with BMP ligand local context specific activation in combination (p < 0.001)." (PMID 40348815, 2025). "The adenoma phenotype was discordant, with reduced small intestinal adenoma burden yet development of large non-metastatic caecal adenoma with nuclear localisation of phospho-Smad2/3." (PMID 40348815, 2025). "Further, the tumor suppressor genes, SMAD2, SMAD4, and BAX, were also involved in the late adenoma stage." (PMID 36499586, 2022).
Alzheimer disease (6 papers, 2012 to 2024). A progressive, neurodegenerative disease characterized by loss of function and death of nerve cells in several areas of the brain leading to loss of cognitive function such as memory and language. "Smad2 is associated with miR-455-3p in various diseases, including Alzheimer’s disease and oesophageal squamous cell carcinoma." (PMID 38654054, 2024). "For example, TGFβ1 inhibits microglia chemotaxis towards amyloid beta aggregates observed in Alzheimer’s disease via activation of TGFβR/SMAD-2-mediated downregulation of the chemokine CCL5." (PMID 30940161, 2019). "Blocking TGFβ-Smad2/3 signaling in innate immune cells reduced deposits of cerebrovascular beta amyloid in the Alzheimer’s disease model." (PMID 28794441, 2017). "In mice exposed to CCl4, Ad-Hep infection notably inhibited Smad3 phosphorylation with minimal inhibition of Smad2 phosphorylation." (PMID 28004654, 2016). "However, in contrast to an expected nuclear localization, phosphorylated Smad2 in Alzheimer’s disease was predominantly, and ectopically, found in the neuronal cytoplasm, specifically colocalized with neurofibrillary tangles and granulovacuolar degeneration." (PMID 22942700, 2012).
diabetic cardiomyopathy (6 papers, 2014 to 2025). Diabetic cardiomyopathy is a disorder of the heart muscle in people with diabetes. "Moreover, miR-30a-5p could also display an antifibrotic action by reducing Smad2 levels in an experimental model of diabetic cardiomyopathy." (PMID 36498905, 2022). "It is now clear that THBS1 is one of the most important physiological activators of TGF-β1, and research has shown that the THBS1-activated TGF-β1/Smad2/3 signaling pathway may play an important role in the development of myocardial interstitial fibrosis in diabetic cardiomyopathy." (PMID 33414684, 2020). "However, whether high glucose induced changes in TGF-β1 activity are dependent upon p300 mediated Smad2 acetylation, and the effect of p300 inhibition upon Smad acetylation in a clinical relevant model of diabetic cardiomyopathy is unknown." (PMID 24886336, 2014).
esophageal squamous cell carcinoma (6 papers, 2012 to 2025). Esophageal squamous cell carcinoma (ESCC) is a type of esophageal carcinoma (EC) that can affect any part of the esophagus, but is usually located in the upper or middle third. "MiR-425 promoted cell proliferation and metastasis by targeting SMAD2 in esophageal squamous cell carcinoma." (PMID 28423650, 2017). "In esophageal squamous cell carcinoma (ESCC), neuronal vesicle trafficking-associated protein 1 (NSG1) amplifies glycolysis and lactate production through activation of the TGF-β/p-SMAD2 axis, which drives epithelial–mesenchymal transition (EMT) and accelerates tumor progression." (PMID 41152975, 2025). "In esophageal squamous cell carcinoma (ESCC), overexpression of RUNX3 remarkably suppresses the phosphorylation of Smad2/3." (PMID 38430423, 2024).
Insulin resistance (6 papers, 2021 to 2026). Increased resistance towards insulin, that is, diminished effectiveness of insulin in reducing blood glucose levels. "Experimental study shows that sEVs from bone marrow stem cells increase the gene expression of insulin signal pathway (insulin, Pdx1, Smad2, Smad3, and transforming growth factor β) in the type 1 diabetes condition and alleviate insulin resistance in the T2D rat model." (PMID 37593852, 2023).
leukemia (6 papers, 2015 to 2026). A malignant (clonal) hematologic disorder, involving hematopoietic stem cells and characterized by the presence of primitive or atypical myeloid or lymphoid cells in the bone marrow and the blood. "The E3 ligase Arkadia (RNF111) targets for proteasomal degradation negative regulators of the TGF-β SMAD2/3 signaling pathway and poly-SUMOylated proteins, e.g., promyelocytic leukemia protein." (PMID 36831384, 2023). "rs4940086 (SMAD2) and rs12803915 (miR-612) are located in potential enhancer regions, based on histone marks, in normal breast, lymphocyte, or leukemia cells." (PMID 27486767, 2016). "Taken together, our results demonstrate that HF inhibits SMAD2 signaling and reduces leukemia growth and angiogenesis." (PMID 26099922, 2015). "We recently demonstrated a direct phosphorylation of AKT and SMAD2 via the TRPM7 kinase, influencing downstream signaling in murine and human immune and leukemia cells, respectively." (PMID 41326173, 2026). "Taken together with our previous report that HF blocked NB4 proliferation and reduced the leukemia burden in vivo we postulated that despite the interference of PML/RARα with TFβR1/SARA/SMAD2/3 complex, the TGF-β pathway remain active in APL and contributes for leukemia progression." (PMID 26099922, 2015).